STAT6 (signal transducer and activator of transcription 6)
Diseases named in the same sentence as STAT6 in open-access papers (continued):
Sharing a sentence is not in itself a finding about the gene and the disease.
solitary fibrous tumor (95 papers, 2015 to 2026). Solitary fibrous tumor (SFT) represents a diverse group of ubiquitous rare spindle cell neoplasms that may be benign or malignant and that most frequently arises from the pleura and peritoneum and rarely from other sites such as head and neck, liver and skeletal muscle. "This can lead to a diagnosis of solitary fibrous tumor, but STAT6 can resolve this diagnostic pitfall." (PMID 41246587, 2025). "DFSP typically exhibits strong CD34 positivity, while other markers, such as S100, SOX10, and STAT6, help exclude neural or solitary fibrous tumor variants." (PMID 41431584, 2025). "The spindle cells show diffuse and strong nuclear expression of STAT6, compatible with the presence of NAB 2-STAT6 fusion and diagnostic of a solitary fibrous tumor." (PMID 37927755, 2023). "NAB2‐STAT6 gene fusion drives STAT6 nuclear expression and is the pathognomonic hallmark of solitary fibrous tumors (SFTs)." (PMID 26686340, 2016). "Initially, ChatGPT-4.0 diagnosed case 18 as a solitary fibrous tumor of the stomach and recommended STAT6." (PMID 40322390, 2025). "On the other hand, expression of STAT6 protein is considered the most specific marker for the diagnosis of solitary fibrous tumors." (PMID 41226013, 2025). "De Novo Analysis, which identifies SVs > 500 bp, detected additional alterations in one tumor, corresponding to a solitary fibrous tumor with a NAB2::STAT6 fusion." (PMID 40141463, 2025). "In 2013, it was discovered that nearly all solitary fibrous tumors have a version of a hallmark intrachromosomal fusion gene between NAB2 and STAT6 on chromosome 12." (PMID 41166819, 2025). "CD34 and STAT6 are important immunohistochemical antibodies for establishing the diagnosis of solitary fibrous tumors, in addition to other immunohistochemical stains as well." (PMID 41226013, 2025). "Background and objectives: Solitary fibrous tumors (SFTs) are morphologically heterogeneous tumors characterized by the NAB2::STAT6 gene fusion." (PMID 39335193, 2024). "STAT-6 is utilized in the diagnosis of solitary fibrous tumors, and CD-117 and DOG-1 are markers specific to GISTs." (PMID 39564019, 2024). "One tumor diagnosed initially as undifferentiated round cell sarcoma harbored NAB2::STAT6 fusion and was reclassified as solitary fibrous tumor (patient #32)." (PMID 38440233, 2024). "The diagnosis of solitary fibrous tumor and tumors of endothelial origin were excluded by the negativity of tumor cells for STAT-6, CD34 and CD31." (PMID 39462411, 2024). "One tumor diagnosed initially as undifferentiated round cell sarcoma harbored NAB2::STAT6 fusion and was reclassified as an aggressive metastatic solitary fibrous tumor." (PMID 38440233, 2024). "Intrachromosomal rearrangements involving STAT6 are characteristic molecular alterations observed in solitary fibrous tumors." (PMID 38275873, 2024). "The tumor cells showed strong and diffuse expression of CD34 and STAT6, confirming the diagnosis of malignant solitary fibrous tumor." (PMID 36817074, 2023). "Solitary fibrous tumor (SFT) is a fibroblastic neoplasm characterized by NAB2::STAT6 gene fusions and can occur in various anatomical sites, displaying a wide morphological spectrum." (PMID 38239634, 2023). "Immunohistochemical analysis for CD13, epithelial membrane antigen, SOX10, and STAT6 was carried out in a large cohort of primary meningeal tumors comprising 225 meningiomas, 15 schwannomas, and 20 solitary fibrous tumor/hemangiopericytomas." (PMID 35212813, 2022). "STAT6 (signal transducer and activator of transcription 6) nuclear immunostaining and/or the identification of NAB2–STAT6 gene fusion is required for the diagnostic confirmation of solitary fibrous tumor." (PMID 34299133, 2021). "Monotonous histology, lack of the pericytomatous pattern of the vasculature, and negativity of STAT6 staining excluded the possibility of solitary fibrous tumor." (PMID 34663426, 2021).
solitary fibrous tumor (continued). "Detection of nuclear STAT6 expression or detection of NAB2-STAT6 fusion is highly recommended to confirm the diagnosis of solitary fibrous tumor/haemangiopericytoma." (PMID 32676456, 2020). "The sensitivity of STAT6 for the diagnosis of solitary fibrous tumors has been reported to range from 86 to 98% in large series at both CNS and soft-tissue sites." (PMID 30584643, 2019). "The use of recently identified antibodies, such as STAT6 for solitary fibrous tumor and TLE1 for synovial sarcoma, are helpful in some settings." (PMID 28145886, 2017). "The signature marker of solitary fibrous tumor is the presence of the NAB2-STAT6 fusion that can be reliably detected with a STAT6 antibody." (PMID 28443588, 2017). "Solitary fibrous tumor has a more prominent hemangiopericytomatous vasculature, and is also immunohistochmically positive for signal transducer and activator of transcription 6 (STAT6) protein." (PMID 26033228, 2015). "Even though STAT6 expression may be present in other mesenchymal tumors, it regularly reveals nuclear positivity in solitary fibrous tumors." (PMID 41226013, 2025). "The absence of STAT6 and H3 K27Me3 loss excludes solitary fibrous tumor (SFT), and the lack of p16 and CDK4 rules out dermatofibrosarcoma protuberans (DFSP)." (PMID 40556675, 2025). "Amplification of MDM2 and positivity for CDK4 are more characteristic of well-differentiated liposarcomas in particular, and though a small percentage can be positive for STAT6, that marker is more specific for solitary fibrous tumors (SFTs) or dedifferentiated liposarcomas." (PMID 41141132, 2025). "Diffuse pan-cytokeratin expression associated with negative STAT6 expression is highly suggestive of an anaplastic carcinoma, rather than solitary fibrous tumors." (PMID 41226013, 2025). "Additionally, the tumor cells were negative for Desmin (arguing against a myogenic tumor), S100 (excluding malignant melanoma and neurogenic tumor), HMB45 (excluding melanoma), and STAT6 (arguing against a solitary fibrous tumor)." (PMID 41584573, 2025). "Additionally, HPCs and solitary fibrous tumors (SFTs) have the same STAT6 nuclear expression and NAB2-STAT6 fusion in the 2016 WHO classification system." (PMID 36386546, 2022). "The identification of a new gene fusion partner for STAT6 in solitary fibrous tumor opens intriguing new hypotheses to refine the role of STAT6 in the sarcomatogenesis of this entity." (PMID 34299133, 2021). "In the present study, a new gene fusion consisting of Nuclear Factor I X (NFIX), mapping to 19p13.2 and STAT6, mapping to 12q13.3 was identified by targeted RNA-Seq in a 74-year-old female patient diagnosed with a deep-seated solitary fibrous tumor in the pelvis." (PMID 34299133, 2021). "HPC has been found to share inversions on the long arm of chromosome 12 (12q13) and a fusion of the NAB2 and STAT6 genes with the solitary fibrous tumor (SFT)." (PMID 40135019, 2025). "Solitary fibrous tumor (SFT) represents a fibroblastic neoplasm exhibiting NAB2::STAT6 gene rearrangement, displaying diverse clinical manifestations, spanning from benign to malignant." (PMID 38239634, 2023). "Immunohistochemistry was STAT6 nuclear positive and cytoplasmic CD34 positive, diagnostic for solitary fibrous tumor (SFT)." (PMID 34707913, 2021). "In the present case, focal positivity for STAT6, Bcl-2, and CD99 supported the diagnosis of dedifferentiated solitary fibrous tumor (DSFT)." (PMID 40728762, 2025). "(c) Most abundant gene fusion present in all solitary fibrous tumors (SFTs) in FFPE RNA-seq, NAB2-STAT6 with exons 1–4 of NAB2 and exons 2–22 of STAT6." (PMID 40875449, 2025). "Solitary fibrous tumor (SFT) is a fibroblastic neoplasm characterized by distinctive thin-walled, branching, staghorn-shaped vessels and the NAB2::STAT6 fusion gene." (PMID 40002892, 2025).
solitary fibrous tumor (continued). "Tumor cells do not express epithelial (CK), myogenic (desmin, SMA), neurogenic (CD56, NSE) markers, well-differentiated/dedifferentiated liposarcoma markers (MDM2, CDK4, p16), or solitary fibrous tumor (SFT) markers (β-catenin, STAT6)." (PMID 41458523, 2025). "Immunohistochemical analysis demonstrated positivity for CD34, STAT6, MyoD1, α-SMA, Bcl-2, and CD99, confirming the diagnosis of extrapleural dedifferentiated solitary fibrous tumor (DSFT)." (PMID 40728762, 2025). "Imaging-guided biopsy revealed an atypical mesenchymal neoplasm with signal transducer and activator of transcription 6 (STAT6) expression, suggestive of a solitary fibrous tumor (SFT)." (PMID 41179270, 2025). "Among these conditions is the intrapulmonary solitary fibrous tumor, which is usually positive for CD34, BCL2, CD99, and, more recently, STAT6." (PMID 40026987, 2025). "These authors noted the importance of nuclear staining for GLI1 and STAT6 for differential diagnosis with GLI tumors and solitary fibrous tumors, which can share similar locations and morphology." (PMID 37108696, 2023). "Positive STAT6 staining in immunohistochemistry and demonstration of NAB2-STAT6 gene fusion on molecular testing can help distinguish solitary fibrous tumors from DFSP." (PMID 36810566, 2023). "All solitary fibrous tumors (SFT), now histologically diagnosed by a positive nuclear STAT6 immunostaining, represent less than 2% of soft tissue sarcomas, with spinal SFT constituting a maximum of 2% of them, making these tumors extremely rare." (PMID 35740510, 2022). "Minimal staining was observed in cases of dedifferentiated liposarcoma (15%) and solitary fibrous tumor (25%), possibly due to the proximity of DDIT3, MDM2 and STAT6 on chromosome 12." (PMID 33921435, 2021). "The lesion was surgically excised revealing the microscopic features characteristic of solitary fibrous tumor, with immunohistochemically reactivity for CD34 and STAT6 stains." (PMID 31777527, 2019). "In the context of solitary fibrous tumor, in NAB2-STAT6 fusion, NAB2 inherits an activation domain from the STAT6, thus converting a ‘transcriptional repressor’ role into a ‘transcriptional activator’ of EGR1." (PMID 31007851, 2019). "A recurring and nonrandom fusion of two genes has been recently identified in solitary fibrous tumor and involves the NGFI-A-binding protein 2 (NAB2) and STAT6 genes, both located at chromosomal region 12q13." (PMID 27672467, 2016). "The fibroblastic cells were positive for STAT6 and sequencing analysis revealed the gene fusion between NAB2 exon 4 and STAT6 exon 2, with which the final diagnos is of solitary fibrous tumor was achieved." (PMID 26425382, 2015). "Some studies showed that the recurrent NAB2-STAT6 gene fusion and STAT6 immunohistochemical expression are present in almost all cases, the last one being especially helpful in identifying CD34-negative solitary fibrous tumors." (PMID 41226013, 2025). "Tumor cells were negative for CD138 (excluding plasmacytoma) and negative for signal transducer and activator of transcription 6 (STAT6) (excluding solitary fibrous tumor)." (PMID 39156287, 2024). "Immunohistochemistry confirmed the diagnosis of a solitary fibrous tumor with positive B-cell lymphoma 2, STAT6, and CD99, negative S100 and smooth muscle actin, and low levels of Ki67 (5–7%)." (PMID 37742027, 2023). "Core biopsy of the 16.5 cm gluteal mass showed a high-grade mesenchymal neoplasm with features reminiscent of a solitary fibrous tumor, but negative for STAT6." (PMID 37865792, 2023). "However, the immunoreactivity for STAT-6, along with a concomitant negativity for WT1, favors the diagnosis of solitary fibrous tumor." (PMID 33445443, 2021). "IHC of signal transducer and activator of transcription 6 (STAT6), which has been used to differentiate solitary fibrous tumors from other soft tissue tumors, yielded negative immunoreactivity." (PMID 33141292, 2020).
solitary fibrous tumor (continued). "Solitary fibrous tumor (SFT) is a fibroblastic neoplasm with NAB2 and STAT6 gene fusion as well as STAT6 nuclear expression." (PMID 42256992, 2026). "Solitary fibrous tumor (SFT) is a rare mesenchymal tumor defined by the NGFI-A binding protein 2 (NAB2)-signal transducer and activator of transcription 6 (STAT6) fusion gene and rarely arises in the sinonasal tract." (PMID 41431481, 2025). "Solitary fibrous tumor (SFT) is also positive for CD34, and characteristically shows nuclear expression of STAT6." (PMID 38609732, 2024). "It is important to note that many liposarcomas and other sarcomas, including intimal sarcoma with MDM2/CDK4 amplification, may exhibit cytoplasmic and/or nuclear expression of STAT6 without necessarily indicating a solitary fibrous tumor." (PMID 38275873, 2024). "Furthermore, CD34, S100, Bcl-2, and STAT-6 expression was negative, ruling out the possibility of a solitary fibrous tumor and malignant peripheral nerve sheath tumor (MPNST)." (PMID 32430041, 2020). "However, according to the latest WHO classification, solitary fibrous tumors can be readily differentiated immunohistochemically from meningioma based on its STAT6 nuclear expression, with the latter being negative for STAT6." (PMID 31520184, 2019). "Moreover, ropey collagen is not common in solitary fibrous tumor, and STAT6 is negative in SC/PL." (PMID 31041916, 2019). "While NAB2:STAT6 fusions are common in solitary fibrous tumors (SFT), we report this event for the first time in a newly diagnosed, secondary-type GBM or any other non-SFT." (PMID 26817999, 2016). "Negative staining for STAT6, ALK and HHV8 effectively excluded solitary fibrous tumors, inflammatory myofibroblastic tumors and Kaposi's sarcoma, respectively." (PMID 40900681, 2025). "Furthermore, STAT6 is considered a highly sensitive marker of solitary fibrous tumor (SFT), and the lack of (a signal transducer and activator of transcription-6 (STAT6) expression can be used to differentiate MCS from SFT." (PMID 37760551, 2023). "Immunohistochemistry (IHC) confirmed the diagnosis of a solitary fibrous tumor with positive B-cell lymphoma 2 (BCL2), STAT6, CD34, and CD99 and negative S100 and smooth muscle actin (SMA)." (PMID 37742027, 2023). "INSM1 was not shown to be useful for solitary fibrous tumor (SFT) diagnosis when compared to HTER and STAT6." (PMID 34943408, 2021). "Additionally, the tumor cells were negative for the signal transducer and activator of transcription 6 (STAT6), CD117, and CD34, which excludes a solitary fibrous tumor and an extra-intestinal gastrointestinal stromal tumor (GIST), respectively." (PMID 40337377, 2025). "Negative staining for MDM2 and CDK4, CD34 and STAT6, and c-kit and DOG1 led to the exclusion of dedifferentiated liposarcoma, solitary fibrous tumor (SFT), and GIST, respectively." (PMID 38739347, 2024).
breast carcinoma (55 papers, 2014 to 2026). "Approximately 2% of HER2-positive breast cancers carry mutations in STAT6, which occur sporadically across the gene." (PMID 32525891, 2020). "We were interested in exploring the effects of STAT6 loss in the context of trastuzumab resistance in HER2+ breast cancers." (PMID 32525891, 2020). "In this study, we explored the effect of STAT6 loss on trastuzumab resistance in breast cancer cell lines." (PMID 32525891, 2020). "In order to determine the role of STAT6 loss on HER2-expressing breast cancer cells, we knocked out STAT6 in the human breast cancer cell line BT-474 to generate clones B1 and B2." (PMID 32525891, 2020). "It has been also shown that the inhibition of the STAT6 pathway in tumour-associated macrophages (TAMs) is a vital therapeutic approach to attenuate tumour growth and metastatic niche formation in breast cancer." (PMID 31075146, 2019). "Although STAT6 deficiency has been reported to suppress tumor progression in mammary cancer and colon carcinoma, our study reveals a different mechanism of action." (PMID 31798581, 2019). "Our results indicated that STAT3, STAT4, STAT5a, STAT5b, and STAT6 were significantly associated with favorable OS in breast cancer patients, especially for high pathological grade patients." (PMID 29326301, 2018). "Indeed, in tumor-associated macrophages, targeting STAT6 was shown to reduce tumor growth and metastatic niche formation in breast cancer." (PMID 36348405, 2022). "Therefore, in order to study the consequences of STAT6 loss in HER2+ breast cancer, we knocked out both alleles of the STAT6 gene using somatic cell gene targeting." (PMID 32525891, 2020). "Our results suggest that STAT6 loss may contribute to trastuzumab resistance in HER2-positive breast cancer cells." (PMID 32525891, 2020). "We were interested in determining if STAT6 loss in HER2+ breast cancers could contribute to trastuzumab resistance." (PMID 32525891, 2020). "Because we found that targeting IL13Rα2 enhances STAT6 phosphorylation by IL-13, we hypothesized that this induction may be implicated in modulating the tumorigenic and metastatic properties of breast cancer cells." (PMID 26208975, 2015). "It is tempting to speculate that altered activity of transcriptional factors, such as Stat6, involved with PR in the (dys)regulation of the p27 gene promoter, could play a role in p27 loss and mammary tumor development." (PMID 24401087, 2014). "The effects of STAT6 loss on breast cancer outcome is unknown." (PMID 32525891, 2020). "In conclusion, our findings highlight the role of JMJD3 in regulating M2-like macrophage polarization and its impact on breast cancer development through the STAT6/IRF4 axis." (PMID 41955245, 2026). "In breast cancer and non-small cell lung cancer, targeting STAT6 or using STAT6 inhibitors can enhance radiosensitivity and reduce M2 polarization of macrophages." (PMID 41585886, 2025). "In the context of cancer, breast cancer lung metastases induce signal transducer and activator of transcription 6 (STAT6)-dependent Th2 cytokine production, which upregulates complement C3 in lung stromal cells." (PMID 40442839, 2025). "In breast cancer, STAT6 plays a key role in inhibiting growth and inducing apoptosis, as it is activated by IL-4 independent of IRS-1." (PMID 40733498, 2025). "STAT6 serves as a potential oncogene causing a variety of human cancers, including CRC, breast cancer, and leukemia by modulating multiple signaling pathways." (PMID 38419894, 2024). "miR-1207 leads to breast cancer cell progression by inhibiting STAT6 which acts as an activator of the cell cycle-dependent kinase inhibitors." (PMID 36624401, 2023). "Of note, both TGFB1 and STAT6 are well-known for their immune evasive roles in breast tumor microenvironment while STAT1 is proposed as a potential biomarker in breast cancer patients undergoing immune checkpoint therapy." (PMID 36809986, 2023).